TYRO3 (TYRO3 protein tyrosine kinase)
Diseases named in the same sentence as TYRO3 in open-access papers (continued):
Sharing a sentence is not in itself a finding about the gene and the disease.
tumor (continued). "In the context of tumors, it was proposed that the zinc finger protein supports the development of a pro-tumorigenic TME, similar to TYRO3, by promoting the polarization of macrophages toward the M2 phenotype and further enhancing tumor progression." (PMID 40415137, 2025). "After the TYRO3 axis is activated, it participates in the communication between cancer cells in the tumor microenvironment." (PMID 40959280, 2025). "For example, it has been demonstrated that in leukaemia activated NK cells transfer tyrosine-protein kinase receptor (TYRO3), a cell membrane protein of Tumor associated macrophage receptor (TAM) family from tumor cells via trogocytosis." (PMID 41181711, 2025). "Meanwhile, blockage of the tyrosine-protein kinase receptor TYRO3 induced ferroptosis in tumor cells and increased sensitivity to immunotherapy." (PMID 40693608, 2025). "Inhibition of TYRO3 promoted tumor ferroptosis and sensitized resistant tumors to anti-PD-1 therapy." (PMID 39128094, 2024). "The TAM (Tyro3, Axl, MerTK) family of RTKs has been shown to provide cancer cells with a strong advantage in proliferation and survival, leading to tumor progression." (PMID 38791148, 2024). "Approximately 42% of patients exhibited Tyro3 overexpression in tumor tissues (>2-fold) and high Tyro3 expression was significantly associated with higher levels of alpha-fetoprotein (AFP)." (PMID 38298195, 2024). "By binding to its receptors (Axl, Mertk, Tyro3), Gas6 is known to significantly affect cell cycle progression in cancer cells, promote angiogenesis, and modulate the immune environment of the tumor." (PMID 39255000, 2024). "Tumor tissues and matched adjacent normal tissue were obtained during resection and Tyro3 gene expression was evaluated." (PMID 38298195, 2024). "Inhibition of TYRO3 promotes tumor ferroptosis and sensitizes resistant tumors to anti-PD-1 therapy." (PMID 38287071, 2024). "Further, Tyro3 was identified as a direct tumor suppressor miRNA gene target that regulates the proliferation, migration, and invasion of human hepatocarcinoma cell lines." (PMID 38791148, 2024). "Concurrently, high expression levels of TYRO3 are associated with resistance to PD-1 inhibitors, and inhibiting TYRO3 can promote tumor cell ferroptosis." (PMID 39430757, 2024). "TYRO3 inhibition led to tumour cell ferroptosis through the AKT‐NRF2 pathway, altering the macrophage ratio and potentially overcoming resistance to anti‐PD‐1 therapy resistance." (PMID 38594879, 2024). "IHC scores indicated that TYRO3 expression level was significantly higher in tumor tissues of CRC patients with TNM stage III-IV than those with TNM stage I-II (P < 0.001)." (PMID 37116196, 2023). "Several studies depicted that the aberrant TYRO3 expression in tumor cells effectively enhances the proliferation and migration of tumor cells." (PMID 37116196, 2023). "This study also demonstrated that TYRO3 is associated with CRC occurrence and development, the prediction effect, and targeted tumor diagnosis and treatment." (PMID 37116196, 2023). "TYRO3 inhibits anti-PD-1/PD-L1-induced ferrogenesis in tumor cells by suppressing the AKT/NRF2 axis and amplifies a favorable tumor microenvironment by reducing the ratio of M1/M2 macrophages, thus contributing to the efficacy of anti-PD-1/PD-L1 therapy." (PMID 36937406, 2023). "The TAM receptor family of tyrosine kinases, MERTK, Axl and Tyro3, inhibition play a role in tumour development in several cancers and a growing body of evidence points towards a role for TAM receptor signalling in the initiation of EMT." (PMID 38102708, 2023). "In the only sample (GSM4909284_TN-MH0114-T2) with relative high expression of TYRO3 (detected in 24% of tumor cells), the actively dividing cells showed higher expression of TYRO3 than other tumor cells (p-value = 0.039, Wilcoxon test)." (PMID 38110427, 2023). "A significant difference in tumor and body weights due to TYRO3 expression was observed between the NC and KD groups in the PC1 axis." (PMID 37116196, 2023).
tumor (continued). "We also analyzed the difference in IHC score between cancer and normal tissues, which showed a more significant TYRO3 expression in tumor tissues (P < 0.001)." (PMID 37116196, 2023). "Our previous findings on the role of ENO1 in tumorigenesis and tumor metabolism enabled the correlation analysis between TYRO3 and ENO1 expression." (PMID 37116196, 2023). "In drug-resistant cell lines H-DR and T-DR, knockdown of TYRO3 also suppressed the proliferation ability in tumor cells." (PMID 37116196, 2023). "This would provide a theoretical basis for reversing tumor cell drug resistance using TYRO3 targeted therapy, a new strategy for treating CRC." (PMID 37116196, 2023). "In contrast, a recent study proposed TYRO3 as an NK cell activating receptor showing that activated human NK cells can acquire the receptor upon contact with tumor cells via trogocytosis and that TYRO3+ NK cells are more cytotoxic and produce more IFN-γ." (PMID 35967396, 2022). "More recently, it was reported that activated human NK cells rapidly acquired TYRO3 from tumor cells via trogocytosis and become more cytotoxic." (PMID 35967396, 2022). "Studies have shown that the expression of TYRO3 is increased in immunotherapy-resistant tumor cells, and TYRO3 signaling pathway inhibits the ferroptosis of tumor cells by up-regulating the expression of SLC3A2 and other genes." (PMID 36387286, 2022). "Genes blocking ferroptosis were upregulated (e.g., Slc40a1, Slc7a11, Slc3a2, and Gpx4) in Tyro3-OE 4T1 tumor cells, whereas genes that induced or enhanced ferroptosis were downregulated (e.g., Slc5a1 and Tfrc), compared with levels in 4T1-P cells." (PMID 35399527, 2022). "In tumor-bearing mice, the expressions of TYRO3, AXL, and MERTK, and their ligands increased >20 folds in M-MDSCs and >15 folds in PMN-MDSCs." (PMID 36131911, 2022). "Of note, the expression of TYRO3, AXL, and MERTK, as well as their ligands, can be dramatically upregulated on immunosuppressive MDSCs in Braf-V600E/Pten deficient melanoma tumor-bearing C57BL/6 mice." (PMID 35572601, 2022). "Mechanistically, TYRO3 facilitated tumor resistance to those ICIs by supporting a “protumor TME” in which the M1/M2 macrophage ratio was reduced." (PMID 36359776, 2022). "Tyro3 expression was decreased in tumor tissues in ESCA and KIRP, predicting worse OS in ESCA but better OS in KIRP; Tyro3 expression was increased in tumor tissues in LIHC and THCA, predicting worse OS in LIHC but better OS in THCA." (PMID 36059952, 2022). "Tumor subtype analyses of LoF variants revealed evidence of association for ZFAND1, TYRO3, DNAH11, and PARP2 with ER-negative breast cancer, with ZFAND1 showing the strongest association (OR = 2.96 (CI 95% 1.59–5.50), p-value = 6.37 × 10−4)." (PMID 35884425, 2022). "The combination of anti-PD-1 antibodies with Tyro3 inhibitors can reverse the responsiveness of resistant tumor cells by stimulating ferroptosis." (PMID 35847022, 2022). "In a syngeneic mouse tumor model and patients receiving anti-PD-1/PD-L1 therapy, tumors expressing a high level of tyrosine-protein kinase receptor (Tyro3) present resistance to anti-PD-1/PD-L1 therapy by inhibiting ferroptosis." (PMID 35847022, 2022). "The crucial role of TYRO3 as a mediator of sunitinib resistance in TH was further experimentally substantiated by overexpression and silencing in tumor cell cultures." (PMID 36230684, 2022). "The inhibition of TYRO3 promoted tumor ferroptosis and sensitized resistant tumors to anti-programmed cell death protein 1 therapy." (PMID 36407322, 2022). "AXL is a member of the TYRO3, AXL, and MERTK (TAM) family of receptor tyrosine kinases (RTKs) that can be activated by the ligand Gas6, which is closely associated with tumor progression." (PMID 36105100, 2022).
tumor (continued). "The TAM receptors Axl, Tyro3, and MerTk were a family of receptor tyrosine kinases, skew macrophage polarization towards a pro-tumor M2-like phenotype in the tumor microenvironment, and promote apoptotic cell clearance through efferocytosis." (PMID 36059952, 2022). "Meanwhile, Tyro3 promotes the development of the original tumor microenvironment by inhibiting ferroptosis of tumor cells induced by anti-PD-1/PD-L1 and reducing the M1/M2 macrophage ratio, thus leading to resistance to PD-1/PD-L1 therapy." (PMID 35528617, 2022). "Extracellular vesicles (EVs) are capable of activating TAM receptors in tumor cells, with most pronounced effects observed for Tyro3." (PMID 34771611, 2021). "In this context, Tyro3 exerts its tumor-promoting functions by downstream activation of Src signaling." (PMID 34771611, 2021). "For example, we observed the interaction between growth arrest-specific 6 (GAS6) expressed by TAMs and its cognate receptor TYRO3 expressed on the cycling tumor cells, which was reported to positively correlate with tumor growth." (PMID 34805184, 2021). "Tumor cells also utilize Tyro3, Axl, and Mer receptor tyrosine kinases to reduce inflammation and innate immune responses." (PMID 33224886, 2020). "TYRO3 was found to be involved in the biological process of immune regulation and promoted tumor cell proliferation, metastasis, and chemotherapy resistance." (PMID 32211443, 2020). "Expression levels for the three receptors and their ligand were heterogeneous in tumours, with only TYRO3 significantly elevated in NMIBCs and MIBCs relative to normal samples." (PMID 30765874, 2019). "In conclusion, we have shown that ProS1 is a tumour-derived functional ligand for Tyro3 that supports cancer cell survival." (PMID 31766614, 2019). "Taken together, our data for the MGH-U3, RT112 and UM-UC-5 cell lines demonstrate that TYRO3 depletion inhibits proliferative pathways and activates tumour suppressor pathways." (PMID 30765874, 2019). "This role is further highlighted in tumours where Tyro3 is present as the sole TAM receptor and is sensitive to stimulation by both vitamin K-dependent TAM ligands." (PMID 31766614, 2019). "TYRO3 is overexpressed in many types of cancer and functions to promote tumor cell survival and/or proliferation, metastasis, and resistance to chemotherapy." (PMID 30501104, 2018). "TYRO3 is expressed on macrophages in the tumor microenvironment, where it functions to suppress anti-tumor immunity." (PMID 30501104, 2018). "Current data suggest that, like other TAM kinases, TYRO3 functions in tumor cells to activate common oncogenic signaling pathways, particularly MEK/ERK and PI3K/AKT; however, other downstream pathways are likely to play critical roles in tumorigenesis as well." (PMID 30501104, 2018). "In these studies, the biochemical mechanisms by which TYRO3 activation can suppress the inflammatory response in the tumor microenvironment were also assessed." (PMID 30501104, 2018). "Subsequent studies to determine the impact of TYRO3 inhibition in a variety of tumor types support roles for TYRO3 in tumor cell proliferation and survival." (PMID 30501104, 2018). "Changes in tumor cell density in response to TYRO3 inhibition are in part due to inhibition of tumor cell proliferation." (PMID 30501104, 2018). "TYRO3 expression also correlated with tumor size of 3 cm or higher; however, on multivariate analysis this association was not statistically significant, potentially due to the limited sample size in this study (n = 55)." (PMID 30501104, 2018). "Here we review the physiological roles for TYRO3 and its expression and functions in cancer cells and the tumor microenvironment, with emphasis on the signaling pathways that are regulated downstream of TYRO3 and emerging roles for TYRO3 in the immune system." (PMID 30501104, 2018).
tumor (continued). "Emerging areas of research include modulation of TAM receptors to enhance anti-tumor immunity, potential roles for TYRO-3 in leukemogenesis, and the function of the bone marrow microenvironment in mediating resistance to TAM inhibition." (PMID 27834816, 2016). "Beside our in vitro findings, that showed a significant inhibition of tumor cell proliferation and increase sensitivity to 5-FU chemotherapy after Tyro3 knockdown in human CRC cells, we where able to show a relevant role in vivo." (PMID 27486820, 2016). "In-vitro inhibition of Tyro3 and Mer reduces tumor cell proliferation and sensitizes tumor cells to chemotherapy." (PMID 27486820, 2016). "In initial experiments, phycoerythrin-conjugated anti-Mer and anti-Tyro3 antibodies were identified that gave positive staining on tumor cell lines known to express Mer (THP-1) and Tyro3 (K562)." (PMID 24650765, 2014). "CXCR4/SDF-1 signaling transcriptionally regulates both Tyro3 and Axl, but silencing of just Axl leads to a decrease in cancer cell invasion, increased apoptosis, and inhibition of tumor formation due to inhibition of angiogenesis." (PMID 25344858, 2014). "70% of the DU145 primary tumor cells expressed Tyro3, while Axl expression was considerably less than observed in cell culture." (PMID 23637920, 2013). "The findings of this study suggest that the expression of Axl and Tyro3 are correlated with tumor growth in animal models of PCa disease." (PMID 23637920, 2013). "In the PC3 system, Axl expression was significantly decreased in the primary tumor compared to cells grown in vitro, while Tyro3 levels were elevated." (PMID 23637920, 2013). "Therefore, the developmentof inhibitors targeting MerTK while avoiding inhibition of Tyro3 holdspromise to suppress tumor growth and alleviate immunosuppression withinthe tumor microenvironment, without inducing neurotoxicity." (PMID 40391976, 2025). "Moreover, TYRO3 regulates the ratio of M1/M2 macrophages to promote the formation of the tumor microenvironment." (PMID 40959280, 2025). "Besides, TYRO3 suppresses tumor cell ferroptosis and promotes tumor survival during anti–PD-1 therapy." (PMID 40175350, 2025). "Turning on TYRO3 helps NK cells grow and keep fighting tumours." (PMID 40088262, 2025). "Overexpression of TYRO3, a receptor tyrosine kinase, supports tumor proliferation and migration." (PMID 40969770, 2025). "Among the prognostic risk model genes, TYRO3 and CPT2 demonstrated strong tumor-suppressive potential, aligning with mRNA-level analyses in which both genes showed negative correlation coefficients within the risk model—further supporting their protective roles in KIRC." (PMID 40969770, 2025). "Blocking TYRO3 can lead to ferroptosis of tumor cells and may be a significant mechanism to minimize resistance to anti-PD-1 therapy." (PMID 38738146, 2024). "However, CD8+T cells can also assume an antioxidant role by decreasing the M1/M2 macrophage ratio and enhancing SLC3A2 expression upon binding to TYRO3, which impedes tumor cell ferroptosis and fosters tumor progression." (PMID 38853203, 2024). "Therefore, the combination of Tyro3 inhibitors with anti‐PD‐1 drugs has the potential to overcome tumour cell drug resistance by promoting ferroptosis." (PMID 38594879, 2024). "Gas6 produced by tumor and ependymal cells was predicted to interact with the receptor Mertk in myeloid cells, Tyro3 in tumor cells and Axl in ependymal cells, while additional App-Cd74 signaling axes were predicted between tumor, myeloid, endothelial and ependymal cells." (PMID 38566128, 2024). "TYRO3 were lowly detected in 7 of the samples (detected in 1–8% of tumor cells)." (PMID 38110427, 2023). "Therefore, targeting TYRO3 is a potentially effective treatment strategy even in drug-resistant tumor cells." (PMID 37116196, 2023).
tumor (continued). "Therefore, the status of tumor invasion, lymph node metastasis, and TYRO3 expression significantly affected the total points, suggesting they had essential roles in predicting CRC patient prognosis." (PMID 37116196, 2023). "Therefore, the tumor growth in the TYRO3-KD group was significantly slower than in the control group when the mice were treated with 5-Fu." (PMID 37116196, 2023). "The results also indicated that TYRO3-KD combined with 5-Fu could inhibit tumor growth significantly." (PMID 37116196, 2023). "Therefore, the correlation between TYRO3 expression and tumor metabolic pathway was further explored to determine its effect on metabolism." (PMID 37116196, 2023). "The growth trend of subcutaneous tumors revealed that the knockdown of TYRO3 expression inhibits tumor growth, and TYRO3-KD combined with 5-Fu could provide a better inhibitory effect." (PMID 37116196, 2023). "After clarifying the difference in TYRO3 expression between tumor and normal tissues, we further assessed whether TYRO3 expression in cancer tissues differed with the TNM stage alteration." (PMID 37116196, 2023). "Moreover, inhibiting TYRO3 expression can significantly inhibit the EMT process in tumor cells and reverse the drug resistance in CRC cells." (PMID 37116196, 2023). "Therefore, targeting TYRO3 is a potentially effective treatment even for drug-resistant tumor cells." (PMID 37116196, 2023). "Based on our study, Tyro3 expression was increased in tumor tissue in LIHC, predicting worse OS." (PMID 36059952, 2022). "It has been reported previously that TYRO3 expression was higher in the patients with lung cancer who were resistant to nivolumab, pembrolizumab, and atezolizumab than that in the patients whose tumor progression was controlled by anti-PD-1/PD-L1 therapy." (PMID 36359776, 2022). "The Tyro3, AXL, and MerTK (TAM) receptor family regulate tumor-associated macrophages that elicit an immunosuppressive tumor microenvironment, and blockade of TAM receptors via cabozantinib may invigorate antitumor immune activation." (PMID 36969746, 2022). "Anti-tumor response of Mertk-/-V1 mice is neither the result of deficient efferocytosis by macrophages nor hypomorphic TYRO3." (PMID 35969037, 2022). "Mechanistically, the authors hypothesized that tumor cells could inhibit ferroptosis through the TYRO3-activated PI3K-AKT-NRF2 pathway to resist the antitumor activity of T cells." (PMID 35399527, 2022). "TYRO3 could serve as a receptor on the surface of macrophages, mediating its interaction with tumor cells and potentiating its polarization toward the anti-inflammatory M2 phenotype." (PMID 35111225, 2022). "In this review, we present and discuss the role of the TAM family (AXL, MERTK, TYRO3) of receptor tyrosine kinases (RTKs) as a dual target in cancer, due to their intrinsic roles in tumour cell survival, migration, chemoresistance, and their immunosuppressive roles in the tumour microenvironment." (PMID 35626092, 2022). "Moreover, Tyro3 also contributes to the generation of a microenvironment that is favorable to tumor growth by reducing the ratio of M1/M2 macrophages." (PMID 35847022, 2022). "ProS is only able to bind to Tyro3 and Mertk, Gas6 can bind to all three TAM receptors (Axl > Tyro3 >>> Mertk), whereas, in a specific tumor microenvironment such as the presence of PtdSer, Mertk and Tyro3 are hyperactivated but their affinities for Gas6 are lower than Axl." (PMID 33509214, 2021). "For AXL-specific or TYRO3-specific inhibitors, the desired anti-tumor immunological effect could be relatively easy to reach as these receptors dominantly function as immune-inhibitory receptors on APCs." (PMID 31664482, 2020). "The present study directly compared both TAM ligands as Tyro3 ligands in native Tyro3-expressing human cancer cell lines, the biological functionality of tumour secreted ProS1, and the diversifying capability of Tyro3 in terms of coupling to intracellular signalling." (PMID 31766614, 2019).